IL18 (interleukin 18)
Diseases named in the same sentence as IL18 in open-access papers (continued):
Sharing a sentence is not in itself a finding about the gene and the disease.
autoimmune disease (105 papers, 2006 to 2025). A disorder resulting from loss of function or tissue destruction of an organ or multiple organs, arising from humoral or cellular immune responses of the individual to their own tissue constituents. "In the present study, we aimed to investigate the serum miRNA levels of autoimmune disease-related miRNAs and their potential association with inflammatory marker IL18 and apoptotic marker sFAS in FMF patients." (PMID 39934489, 2025). "Due to its critical role in immunity, IL-18 is implicated in several autoimmune diseases, such as psoriasis, systemic lupus erythematosus MS, as well as in infectious diseases like SARS-CoV-2." (PMID 40507498, 2025). "IL-18 and IL-18BP are associated with various diseases, including autoimmune disorders, inflammatory conditions, infectious diseases, and cancer (Mühl & Bachmann, 2019)." (PMID 39769266, 2024). "Clinical studies have confirmed this duality: IL-18 can be harmful in autoimmune diseases and conditions involving rare mutations, yet beneficial in pathogen defense and certain cancers." (PMID 39769266, 2024). "SHRs are particularly prone to excessive inflammatory responses in various organs, including the spleen, pancreas, liver, heart, kidney, and brain, where elevated IL-18 levels have been linked to autoimmune diseases and nephropathy progression." (PMID 39513878, 2024). "IL-18 has been implicated in several autoimmune diseases including MS, because it stimulates γδ T cells to express IL-17 and promotes the production of the Th1 cytokine IFNγ from T cells and NK cells." (PMID 37414913, 2023). "Consistent with this pro-inflammatory role of IL-18, several autoinflammatory and autoimmune diseases are associated with increased serum concentrations of IL-18 including CAPS, FMF, and MS." (PMID 35832789, 2022). "NLRP3 inflammasome, which is activated upon signs of cellular “danger” to trigger innate immune defense through the maturation of pro-inflammatory cytokines such as IL-1β and IL-18, is reported to be closely associated with autoimmune diseases." (PMID 35965334, 2022). "Excessive IL-18 is associated to the development of autoimmune diseases, and the increased levels of IL-18 and of its inhibitor IL-18BP are a common marker of ongoing inflammation and ageing." (PMID 35464444, 2022). "IL-18 activity has previously been linked to several autoimmune diseases, and preventing IL-18 from binding to IL-18R1 reduces the risk of inflammatory diseases." (PMID 34878845, 2021). "In agreement, the majority of IL-18 associated autoimmune diseases result from excess Th2 immune responses, potentially from IL-18 activity without IL-12 or IL-15." (PMID 33643264, 2021). "IL-1β, IL-18, and NO have been highlighted by numerous studies as essential mediators of inflammation and have been implicated in autoimmune diseases and other inflammatory conditions." (PMID 32646056, 2020). "The action of IL-18 is tightly regulated by IL-18 binding protein (IL-18BP) and in autoimmune diseases, the serum IL-18/IL-18BP ratio is associated with disease severity." (PMID 31978079, 2020). "Genetic polymorphisms have also been reported in the IL-18 or IL-18 receptor genes of patients with autoimmune diseases, allergic reactions, and neurological/metabolic syndromes." (PMID 30992532, 2019). "Excessive inflammasome activation can promote excessive release of IL-1β and IL-18, causing autoinflammatory disorders and the subsequent development of autoimmune diseases, such as SLE." (PMID 30534157, 2018). "IL-18 is associated with the pathogenesis of a number of renal disorders, such as autoimmune diseases." (PMID 29514661, 2018). "In summary, using a genetic approach, we provide evidence that IL-18 plays a minor role in the autoimmune disease in MRLlpr mice, essentially confirming the data observed in IL-18-deficient lupus-prone C57Bl/6 mice." (PMID 26465326, 2015).
autoimmune disease (continued). "The IL18 gene is located on chromosome 11q22.2–22.3 with six exons and five introns, and many studies show IL-18 gene promoter polymorphisms are associated with autoimmune diseases (RA and SLE),especially the IL-18 gene rs1946518 and rs187238 polymorphisms." (PMID 23153245, 2012). "Taken together, the different results in terms of disease susceptibility mediated by the IL18 gene polymorphisms in different autoimmune diseases support the notion that different pathogenic mechanisms are involved in the development of polygenic diseases." (PMID 20331879, 2010). "Promotor SNPs (-607, -137) in the IL18 gene, which has shown association with several autoimmune diseases, initially suggested association with CD (P < 0.05)." (PMID 20478055, 2010). "IL18 gene is located on chromosome 11q22.2-22.3 and several polymorphisms within the IL18 promoter gene have been associated with different inflammatory and autoimmune diseases." (PMID 20331879, 2010). "Moreover, single nucleotide polymorphisms (SNPs) play a crucial role in autoimmune diseases, and they can affect the priming of inflammasomes, some of their components or end products (IL-1β, IL-18)." (PMID 35457026, 2022). "It encodes IL-18 which contributes to the pathogenesis of autoimmune diseases and inflammation." (PMID 30787914, 2019). "Several human autoimmune diseases are associated with elevated production of IFNγ and IL-18." (PMID 24115947, 2013). "Interleukin 18 (IL-18) is a pro-inflammatory cytokine that has been implicated in the pathogenesis of many inflammatory renal disease, including renal ischemia-reperfusion injury, allograft rejection, autoimmune disease, and recently, obstructive uropathy." (PMID 23077611, 2012). "IL18 promoter gene polymorphisms have been associated with several autoimmune diseases." (PMID 20331879, 2010). "Several autoimmune diseases associated with increased interferon-gamma levels, such as macrophage activation syndrome, rheumatoid arthritis, Crohn's disease, psoriasis, and graft-versus-host disease are thought to be mediated in part by IL-18." (PMID 27713252, 2010). "Additionally, IL-18 plays a vital role in the regulation of innate and adaptive immunity, where abnormal regulation may cause various autoimmune diseases." (PMID 35931995, 2022). "Interleukin-18 (IL-18), an IL-1 family cytokine with potent ability to induce interferon gamma production and enhance Th1 response, was elevated in a group of autoimmune diseases including primary Sjögren syndrome (pSS)." (PMID 40128067, 2025). "M1 macrophages are an important source of many inflammatory cytokines, including TNF-α, IL-1, IL-12, IL-18, and IL-23, which have been identified as important mediators and drivers of chronic inflammatory and autoimmune diseases." (PMID 39858200, 2025). "Overall, IL-18 plays an important role in regulating innate immunity and autoimmune diseases and can be activated by ccf-mtDNA, which promotes the assembly of NLRP332 and the pyroptosis signalling cascade." (PMID 40248349, 2025). "Dinarello revisited the role of IL-18 in autoimmune diseases and the activity of its natural regulator, IL-18 binding protein (IL-18BP)." (PMID 41417343, 2025). "Targeting IL-18 was found to be effective in experimental models of autoimmune diseases including inflammatory bowel disease and rheumatoid arthritis, as well as to be safe in clinical patients." (PMID 39445015, 2024). "As observed in the majority of the reviewed articles, biomarkers like S100 proteins or the cross-activation of cytokines (IL-17, IL-18, IL-6) are evident across various autoimmune diseases." (PMID 38474052, 2024). "The importance of the IL-18/IL-18BP dyad lies in its ability to balance the immune system, making it a potential therapeutic target for autoimmune disorders, inflammatory diseases and cancer, conditions that require precise immune modulation." (PMID 39769266, 2024).
autoimmune disease (continued). "In Th1-dominated immune responses, IL-18 enhances the activity of NK cells and cytotoxic T cells, e.g., to combat intracellular pathogens, fight cancer cells, and trigger autoimmune diseases." (PMID 39769266, 2024). "IL-18 knockout (KO) mouse models provide insights into the multifaceted roles of IL-18 in immune regulation, inflammation, autoimmune diseases, infectious diseases, metabolic disorders, and cancer." (PMID 39769266, 2024). "IL18RAP is associated with a variety of autoimmune diseases including lupus, celiac, but especially with CAD via whole blood expression levels, and associated with MI via IL18 SNPs." (PMID 38978787, 2024). "IL-18 KO mice showed reduced severity in models of autoimmune diseases, e.g., arthritis, lupus, and inflammatory bowel disease (IBD) pointing to the deleterious effect of an excess of IL-18 in human diseases." (PMID 39769266, 2024). "As an important regulator for both innate and acquired immune response, IL18 plays an important role in inflammatory/autoimmunity diseases." (PMID 37605653, 2023). "Not only is IL-18 linked to autoimmune diseases such as T1D and SLE, IL-18 has also been shown to play a key role in the maintenance of the intestinal epithelial barrier and regulation gut microbiota composition." (PMID 37081890, 2023). "IL-18 is a member of the IL-1 cytokine super family and is expressed in inflammation, autoimmune diseases, various cancers, and many infectious diseases." (PMID 36675746, 2022). "Uncontrolled mature IL-18 secretion and IL-1β is responsible for severe autoimmune disorders as they bind to their receptors, initiate several signaling, and ultimately activate NF-kB." (PMID 36032110, 2022). "Together with other cytokines, increased expression of IL-18 contributes to macrophage activation syndrome, a condition seen in autoimmune diseases and influenza." (PMID 36111789, 2022). "This clearly shows that IL-18 cytokine has a role in the progression or development of some inflammatory and autoimmune diseases." (PMID 36032110, 2022). "Despite a large number of reports that have indicated the indispensable role of IL-18 in autoimmune diseases, many of them are still elusive." (PMID 36032110, 2022). "We found that POTS patients had elevations of the proinflammatory cytokines IL-1β, IL-6, IL-18, and INFΥ, which have been reported in both autoinflammatory and autoimmune diseases and, potentially, are a result of abnormal NK cell function." (PMID 35269395, 2022). "In the present review, we aimed to summarize the biological properties of IL-18 and its pathological role in different autoimmune diseases." (PMID 36032110, 2022). "The broad biological role of the IL-18 cytokine on immune cells have revealed its potential role in inflammatory and autoimmune diseases." (PMID 36032110, 2022). "MRL/lpr mice, which develop spontaneous lupus-like autoimmune disease, had higher levels of serum IL-18 compared to controls, and the mice treated with IL-18 developed accelerated proteinuria, glomerulonephritis and vasculitis." (PMID 33732720, 2021). "We assume an upregulation of IL18BP in IBDV-infected BF of chickens as a self-negative regulation mechanism to reduce inflammation inside the bursal tissue as targeting IL-18 with IL18BP is an achievable treatment for autoimmune disease in humans." (PMID 34147086, 2021). "It has been reported that inflammatory cytokines IL-1 β and IL-18 can induce Th17 response and endothelial cell damage, aggravate many autoimmune diseases." (PMID 33679890, 2021). "Both IL-1β and IL-18 play crucial parts in the pathogenesis of a range of inflammatory and autoimmune diseases." (PMID 35008798, 2021). "IL-18 plays a key role in the polarized type 1 innate and adaptive responses that can possibly extend to the mediation of autoimmune diseases." (PMID 33652679, 2021).
autoimmune disease (continued). "Autoimmune disorders are propelled by type I interferon, whereas autoinflammation is distinguished by elevations of inflammasome-induced IL-1β and IL-18; IL-1β and type I IFN counter-regulate one another and interfere with adaptive immune responses." (PMID 33562074, 2021). "If these clinical trials are proved effective, it will be possible to extend inhibitors of IL-18 to the treatment of other autoimmune diseases with abnormally high level of IL-18." (PMID 35095918, 2021). "IL-18 contributes to autoimmune disease including Type-1 diabetes, psoriasis, IBD, asthma and numerous myocardial and kidney diseases." (PMID 33643264, 2021). "IL-1β and IL-18 are the major inflammatory cytokines activated by various types of inflammasomes and are involved in the pathogenesis of several autoimmune diseases." (PMID 35095918, 2021). "IL-18 is involved in the initiation of severe inflammatory responses, indicating the role of IL-18 in inflammatory and autoimmune disorders." (PMID 32045425, 2020). "Although dysfunction of IL-18 has been previously observed in inflammatory and autoimmune diseases, recent research has shown that IL-18 is also a key regulator of proliferation in some tumors." (PMID 33294056, 2020). "Uncontrolled secretion of mature interleukin (IL)-1β and IL-18 is responsible for severe autoinflammatory or autoimmune disorders and various allergic diseases." (PMID 30992532, 2019). "Various animal models of autoimmune diseases have demonstrated the importance of IL-18 as an immune regulatory cytokine." (PMID 29854762, 2018). "TNFR2, IL-1ra, and IL-18 are inflammatory markers that are present at increased levels in a variety of autoimmune diseases, including psoriasis." (PMID 28723914, 2017). "Being a pleiotropic cytokine IL-18 can also stimulate severe inflammatory reactions that establish its role in most inflammatory and autoimmune diseases." (PMID 25822970, 2015). "IL-12 is involved in many autoimmune diseases, including MS (and EAE); IL-18 is also a major cytokine whose role in driving autoimmune diseases but also hypersensitivity conditions is gaining strong interest." (PMID 26483793, 2015). "Because IL-18 can increase IFNγ production, blocking IL-18 activity in autoimmune diseases is an attractive therapeutic target since anti-IL-12/23 reduces the severity of Crohn’s disease as well as psoriasis." (PMID 24115947, 2013). "IL-18 is a cytokine with a wide range of biological activity in various infectious diseases and autoimmune diseases." (PMID 24312909, 2013). "It is also possible that AA activated lymphocytes release IL18 into circulation as observed in other autoimmune diseases." (PMID 23658656, 2013). "IL-18 from the serum of autoimmune disease patients were also slightly up-regulated compared with healthy volunteers." (PMID 19325795, 2008). "Several dendritic cell-derived cytokines, such as IL-12, IL-18, and IL-23, are known activators of T cells and important cytokines in the pathogenesis of autoimmune diseases." (PMID 17078892, 2006). "Their upregulation in NK and T cells in the AC mouse model correlated with enhanced IFN-γ signaling, consistent with a model in which IL-18 signaling contributes to IFN-γ production and with previous reports implicating IL-18 in allergic and autoimmune diseases." (PMID 41476961, 2025). "IL-18 is a proinflammatory cytokine that is secreted by macrophages and MAIT cells in response to viral and bacterial infections, but its overproduction has been associated with autoimmune diseases." (PMID 38571946, 2024). "Other studies have identified IL-18 as an inducer of Th-1 autoimmune diseases." (PMID 38730712, 2024). "For example, in autoimmune diseases characterized by excessive IL-18 activity, blocking IL-18 or enhancing IL-18BP function could be beneficial." (PMID 39769266, 2024).
autoimmune disease (continued). "IL-18 also serves various functions, including IFNγ induction, NK cell activity reinforcement, cytotoxic function enhancement, and promoting inflammatory responses and autoimmune diseases." (PMID 38140264, 2023). "Here, we mentioned the contribution of IL-18 to several autoimmune diseases." (PMID 36032110, 2022). "Immunopathogenic mechanism of interleukin 18 involvement in autoimmune diseases." (PMID 36032110, 2022). "Since IL-18 is a proinflammatory cytokine and its measurement may also be influenced by many coexisting variables including endotoxemia, inflammation, and autoimmune diseases, its sensitivity and specificity could be affected." (PMID 36259446, 2022). "A study found that rapamycin decreased macrophage secretion of IL-18 and IL-1β by reducing caspase-1 activation, indicating that inhibition of mTOR may be advantageous for patients with inherited autoimmune diseases." (PMID 36595872, 2022). "For instance, the definitive steps required in IL-18 signaling and activation triggers in different autoimmune diseases are widely unknown." (PMID 36032110, 2022). "Collectively, the effect of NLRP3 inflammasome in autoimmune diseases involves the following two aspects: due to caspase-1 being the effector of inflammasome structure, IL-1β, IL-18, and pyroptosis modulated by activated caspase-1 play a major role in autoimmune diseases." (PMID 34707607, 2021). "In addition to it acting in both acquired and innate immunity, IL-18 is also involved in chronic inflammation, autoimmune diseases and several cancers." (PMID 34444668, 2021). "Moreover, the IL-1F, for instance, IL-18, participated in regulating the immune response in autoimmune diseases and provided opportunities for new therapies of autoimmune diseases." (PMID 34539413, 2021). "The prognostic value of IL-18 has also been identified in various autoimmune diseases and inflammatory diseases such as rheumatoid arthritis, insulin-dependent diabetes, and multiple sclerosis; the IL-18 precursor is expressed in various cell types throughout the gastrointestinal tract." (PMID 33660570, 2021). "GSDMD encodes a member of the adermin family of pore-forming proteins implicated in the immune response, which controls the release of the proinflammatory cytokines IL-1ß, IL-18 and pyroptotic cell death, and drive the inflammation in septic shock as well as the autoimmune diseases." (PMID 33255903, 2020). "Indeed, blocking the action of IL-18 using recombinant human IL-18BP (Tadekinig Alfa) is in late stage clinical trials for a number of autoimmune disorders." (PMID 31978079, 2020). "IL-18 and IL-12 synergistically stimulate the production of interferon gamma (IFNγ) by T lymphocytes and NK cells altering the transcription of more than 30 genes to elicit a number of inflammatory and autoimmune diseases." (PMID 33228660, 2020). "Both NLRC4 and IL-18 take parts in a variety of inflammatory and autoimmune diseases." (PMID 32802832, 2020). "Some human autoimmune diseases are associated with the elevated production of IFN-γ and IL-18." (PMID 31182982, 2019). "Autoimmune diseases such as systemic lupus erythematosus, rheumatoid arthritis (RA), type-1 diabetes mellitus, Crohn’s disease and psoriasis, and graft versus host disease are thought to be mediated by IL-18." (PMID 31182982, 2019). "Interleukin-18 (IL-18) is a pro-inflammatory cytokine that is found in autoimmune disorders." (PMID 28448439, 2017). "ABT-325 is a humanized anti-IL-18 mAb which is entering clinical trials in autoimmune diseases." (PMID 27713252, 2010). "Furthermore, increased serum levels of IL18 have been identified in patients with autoimmune diseases such as RA and acute asthma." (PMID 20478055, 2010). "IL-18 has also emerged as a pivotal cytokine in different autoimmune diseases." (PMID 20331879, 2010).